IFNG (interferon gamma)
Diseases named in the same sentence as IFNG in open-access papers (continued):
Sharing a sentence is not in itself a finding about the gene and the disease.
lupus (continued). "DN cells are also expanded in autoimmune disease such as Systemic Lupus Erythematosus (SLE) where they are responsive to IFNγ and thought to be precursors for pathogenic antibody secreting cells." (PMID 33815362, 2021). "Furthermore, IFNγ production by CD4+ T cells is enhanced by several lupus associated stimuli." (PMID 33519824, 2020). "Recent studies have shown that genetic variants in TBX21 and IFNG are connected with risk of systemic lupus erythematosus (SLE)." (PMID 26916970, 2016). "This IFNG SNP correlated (p = 0.0024) with systemic lupus erythematosus in a study involving 1759 Korean participants." (PMID 39860482, 2025). "IFNγ signaling on B cells through the IFNγ receptor (IFNγR) is required for the development of follicular T cells and germinal centers in lupus-prone B6.Sle1b mice." (PMID 40943602, 2025). "Instead, by sequencing sorted cells from young lupus-prone mice, we identified an “IFNγ response” and “phagocytosis regulation” microglial signature." (PMID 40048256, 2025). "High levels of proteinuria and hematuria combined with unstable levels of IL10 and IFNγ promote the development of severe lupus and shorten the survival of treated MRL/lpr mice." (PMID 40806179, 2025). "IFNγ is produced by a wide range of lymphocytes, but during severe lupus, expanded B220+ DN T-cells are the major producers." (PMID 40806179, 2025). "Our study revealed that microglia in the brains of lupus mice showed specific activation of ‘phagocytosis, recognition’, ‘response to interferon gamma’ and ‘cellular response to lipopolysaccharide’." (PMID 38494844, 2024). "In lupus-prone Roquinsan/san mice, reduced IFNγ decay led to much IFNγ signaling in T cells, accumulation of Tfh cells, spontaneous germinal center formation, ANA production, and severe nephritis." (PMID 38164134, 2023). "When discussing the role of IFNγ in lupus development or potential of targeting IFNγ in lupus, both lupus mouse models and SLE patients with in vivo studies have implied a significant association of IFNγ and lupus." (PMID 38164134, 2023). "The enhanced glycolysis and OXPHOS found in naive CD4+ T cells from lupus-prone mice correlated with cellular activation status, especially excessive interferon gamma (IFNγ) production." (PMID 37554724, 2023). "CD11c+T-bet+ ABCs in lupus mice showed a hypermetabolic state with elevated glycolytic capacity, which will be further upregulated by stimulation with IFNγ." (PMID 38164134, 2023). "In MRL/lpr mice, administration of the artemisinin analog SM934 ameliorated lupus development and suppressed serum levels of IFNγ but increased the expression of Foxp3 in Treg cells." (PMID 38164134, 2023). "By targeting overactive effector T cells, including Th1 and Th17 cells, as well as proinflammatory cytokines such as interferon interferon-gamma (IFN-γ) and IL-17, metformin shows potential in reducing inflammation in Systemic Lupus Erythematosus (SLE)." (PMID 37881440, 2023). "IFNγ, the main cytokine produced by Th1 cells, has been found to be upregulated in most spontaneous lupus mouse models including (NZB×NZW)F1, B6.Sle1b and MRL/lpr." (PMID 35055071, 2022). "Previous studies have reported that E2 can regulate the production of IFNγ in vitro, and oestradiol can regulate type I and II IFNs production in systemic lupus erythematosus." (PMID 36016428, 2022). "Here we show that in the presence of interferon gamma (IFN-γ), a short DRB1*03:01-encoded allelic epitope activates a characteristic lupus transcriptome in mouse and human macrophages." (PMID 35902632, 2022). "Within the CD4+ T helper cell population, both Th1 and Th17 cells and their cytokine products, IFNγ and IL-17, have been found to be elevated relative to Treg cells in lupus-prone mouse models." (PMID 35055071, 2022). "One study has identified the estrogen receptor alpha (ER-α) gene (ESR1) as a target induced by both IFNα and IFNγ in distinct cell types, including splenic cells, from lupus mice." (PMID 34733276, 2021).
lupus (continued). "LDGs from patients with SLE (systemic lupus erythematosus) induced T cells to produce significantly higher levels of interferon gamma (IFN-γ) and tumor necrosis factor alpha (TNF-α), two proinflammatory cytokines, compared to NDNs." (PMID 34578124, 2021). "4MU also reduced infiltration of T cells into the kidneys and reduced the total number of CD4+IFNG+ cells in the spleens of lupus prone MRL/lpr mice." (PMID 34665782, 2021). "Previous studies have demonstrated that genetic polymorphisms of IFNG and IFNGR1 were correlated with tuberculosis infection, systemic lupus erythematosus, etc.." (PMID 34646402, 2021). "In particular, neutrophils can contribute to excess serum BAFF levels, through which they have been demonstrated to promote CD4+ T-cell and B-cell responses and enhance CD4+ T-cell proliferation and IFNγ secretion in lupus-prone mice." (PMID 34211466, 2021). "Our in vitro data suggest a positive role of EGR2 in the regulation of Th1 differentiation and IFNγ production in lupus effector CD4+ T cells." (PMID 32646370, 2020). "Treatment of triple congenic B6.Sle1.Sle2.Sle3 lupus-prone mice with metformin, the inhibitor of mitochondrial metabolism, corrected abnormal T cell metabolism, reduced IFNγ production and restored the IL-2 production." (PMID 32257420, 2020). "We further demonstrated that EGR2 plays a differential role in a lupus context since it positively regulated Th1 differentiation and IFNγ production in CD4+ T cells from MRL-lpr lupus mice." (PMID 32646370, 2020). "These include the role of PI3K signaling in B cell tolerance, a requirement for B cell intrinsic interferon gamma (IFNγ) signaling for autoantibody production, and altered chromatin accessibility in lupus B cells." (PMID 33519824, 2020). "Both CD4+ and CD8+ T cells contributed to the overproduction of inflammatory cytokine IFNγ in human lupus patients." (PMID 32646370, 2020). "Previous studies showed IFNγ and IL-17A, derived from Th1 and Th17 cell respectively, played a pathology role in lupus progress in MRL/lpr mice." (PMID 33597869, 2020). "Higher IFNγ production was found in total PBMCs that were stimulated with NETs from lupus patients that previously had shown to contain ISG15 compared to cells stimulated with NETs from healthy controls (%IFNγ 6.5[6.31–10.1] vs 3.5[1.7–5.1]) p < 0.05)." (PMID 33176801, 2020). "The role of IFNG in the pathogenesis of human lupus has been inferred largely through in vitro experiments." (PMID 31044165, 2019). "Administration of IFN-γ accelerates murine lupus while early treatment with anti-IFNγ antibody rescues mice from disease." (PMID 30524430, 2018). "Interferon gamma (IFN-γ) is predominantly produced by T cells and natural killer cells, and it plays a critical role in lupus." (PMID 28841837, 2017). "High levels of IFNγ, in contrast, enhance the production of complement-fixing IgG subclass of autoantibodies in lupus mice and promote lupus disease in patients with RA when treated with the cytokine." (PMID 28456914, 2017). "The type II interferon-gamma (IFN-γ) plays a positive role in Tfh differentiation as accumulation of Tfh was observed due to excess IFN-γ as shown in the Sanroque Lupus model." (PMID 27933060, 2016). "Abnormal production of inflammatory cytokines such as IFNγ, IL-1β, IL-6, and TNFα is a key characteristic of lupus." (PMID 27070142, 2016). "We also show that neutrophils from BCMA deficient lupus-prone mice induce CD4+ T cell proliferation and IFNγ production in a BAFF-dependent manner more potently compared to neutrophils from BCMA sufficient lupus-prone mice." (PMID 25010693, 2014). "Neutrophils from BCMA-deficient lupus-prone mice cultured with wild-type CD4+ T cells significantly promoted T cell proliferation and the production of IFNγ compared to neutrophils from control mice." (PMID 25010693, 2014).
lupus (continued). "Long-term depletion of neutrophils using the mAb, 1A8, significantly reduced the frequency of IFNγ-producing CD4+ T cells and the autoimmune phenotype in BCMA-deficient lupus-prone animals." (PMID 25010693, 2014). "Analysis of serum IFNγ titers in lupus-prone mice demonstrated significantly higher levels from B6.Faslpr/JTnfrsf17−/− mice with age compared to B6.Faslpr/J mice and control animals, which had little IFNγ." (PMID 25010693, 2014). "We found that Gal-9 decreased the frequency of Th1 (IFNγ+ IL-4− CD3+ CD4+ cells) significantly, while Th2 (IL-4+ IFNγ− CD3+ CD4+ cells) were unchanged in Gal-9-treated MRL/lpr lupus-prone mice." (PMID 23585851, 2013). "Furthermore, while we have identified IFN-γ as an important factor causing reduced Ahrr in lupus intestines, the reasons for the significant increase of IFNG in intestines of lupus still require further investigation." (PMID 39871323, 2025). "IFNγ is responsible for Th1 stimulation and activation, strongly promoting lupus progression." (PMID 40806179, 2025). "The PVAT in lupus mice exhibited increased infiltration of immune cells and expression of pro-inflammatory cytokines (e.g., IL-1β, IL-6, TNFα, IFNγ), along with decreased expression of adiponectin, which likely promotes endothelial dysfunction and vascular wall remodeling." (PMID 37006244, 2023). "Importantly, expression of pro-inflammatory cytokines (IL-1β, IL-6, TNFα and IFNγ) was increased in PVAT from lupus mice, concomitant with elevated plasma levels of TNFα, IFNγ and IL-6." (PMID 37006244, 2023). "However, stimulating CD11b+ cells with piceatannol blunted ROS production, indicating that IFNγ licenses CD11b+ cells in lupus by regulating Syk signaling." (PMID 38164134, 2023). "To determine whether miR-183C miRNAs play a role in regulating lupus-related inflammatory cytokines such as IFNγ and IL-6, we inhibited miR-182 alone or miR-183C miRNAs with specific antagomirs in vitro in splenocytes." (PMID 35873462, 2022). "This study reports that in vitro inhibition of miR-182 alone or miR-183C by specific antagomirs in activated splenocytes from autoimmune-prone MRL/lpr and control MRL mice significantly reduced lupus-related inflammatory cytokines, interferon-gamma (IFNγ), and IL-6 production." (PMID 35873462, 2022). "Remarkably, pathogenic anti-DNA autoantibody inducing Th cells in human lupus recognized the same immunodominant histone peptide autoepitopes identified in murine lupus, and those T cells in lupus patient’s PBMC respond by producing IFNγ." (PMID 33936042, 2021). "In lupus, both IFNα and IFNγ have been suggested as drivers of disease." (PMID 34220829, 2021). "Importantly, restoration of bacterial DNA in the antibiotic-treated mice increased the abundance of Breg cells in the spleen and MLN at 8 weeks of age, downregulated IL-17 and IFNγ related immune responses, and significantly attenuated lupus." (PMID 33240280, 2020). "Thus, in the lupus prone environment B cells can have both increased access and responsiveness to IFNγ." (PMID 33519824, 2020). "However, of late there has been a resurgence in the study of interferon gamma (IFNγ) in lupus, particularly in the context of B cell responses." (PMID 33519824, 2020). "BAFF can also act directly on T cells to increase IFNγ expression in the Lyn-/- model of lupus." (PMID 33519824, 2020). "Several factors have been found to facilitate the ability of B cells to respond to IFNγ in lupus." (PMID 33519824, 2020). "Early reduction of circulating bacterial DNA by vancomycin treatment significantly decreased the percentage of Breg cells in the spleen, resulting in higher levels of IFNγ production, IL-17 mRNA expression, earlier disease initiation, and exacerbation of lupus." (PMID 33240280, 2020). "A previous study by Mardaniet al. showed that an intervention with probiotics could reduce IFNγ and IL-17 levels in pristane induced murine lupus, followed by a reduction in autoantibodies such as ANA, anti-dsDNA and anti-RNP9." (PMID 34386197, 2020).
lupus (continued). "Faslpr and pristane induced mouse model of lupus, however, due to the crucial role of IFNγ in antiviral immunity in humans, the usefulness of IFNγ blockade in SLE may be limited." (PMID 31354738, 2019). "In lupus mouse models, IFNG appears to play a more prominent role than in humans, and we hypothesize the presence of IFNG may represent a late stage response to the inappropriate induction of type I IFNs to sterile inflammatory stimuli." (PMID 31044165, 2019). "As HPK1 acts as a negative regulator of T cell-mediated IFNγ and IgG production, it may explain part of the lupus pathophysiology." (PMID 30545086, 2018). "Finally, inhibition of select DLK1-Dio3 miRNA such as miR-154, miR-379 and miR-300 with specific antagomirs significantly reduced the production of lupus-relevant IFNγ, IL-1β, IL-6, and IL-10 in lipopolysaccharide (LPS) activated splenocytes from MRL-lpr mice." (PMID 27070142, 2016). "In the case of murine lupus, contribution of IFNγ is well known." (PMID 25285625, 2014). "In addition, ablation of IFNγ signaling provided protection against the disease in a T-cell-dependent model of lupus." (PMID 25147296, 2014). "For example, IL-6 levels increased in response to a cold pressor task in patients with RA and juvenile idiopathic arthritis, but IL-6 and IFNγ levels remained unchanged after psychological stress was induced in patients with RA and systemic lupus erythematosus." (PMID 24274618, 2013). "Thus, we both demonstrate the increased prevalence of NKG2C+ CD8+ T cells in patients with lupus, but we also experimentally validated their inflammatory SLEC-like phenotype that may, possibly through IFNγ secretion, allow them to play pathogenic roles." (PMID 38427562, 2024). "Previous studies have shown that deletion of IL-23R in B6/lpr and MRL/lpr mice reduced DN T, IFNγ- and IL-17- producing cells, suppressed anti-dsDNA autoantibodies and total IgG production, reduced immune complex deposition, and ameliorated lupus nephritis in the lpr lupus mice." (PMID 35784356, 2022). "Indeed, Ig class-switch recombination (CSR), during T and B cell cognate interaction, which is Th1 IFNγ cytokine dependent in lupus, may occur before the TFH IL-21 driven expansion of autoantibody producing B cells in germinal center, which comes later." (PMID 33936042, 2021). "Furthermore, in this model of IFNγ deficient mice, post pristane induction, no antibodies characteristically associated with lupus, such as IgG anti-ssDNA and anti-chromatin antibody, were found." (PMID 34386197, 2020). "T cells from SLE patients and lupus-prone mice have expanded T helper 1 (Th1), Th17, follicular, and extrafollicular helper T (Tfh and eTfh) cell subsets, which contribute to the inflammation and autoreactive antibody production through increased IFNγ, TNFα, IL-6, IL-17, and IL-21 secretion." (PMID 32849532, 2020). "A comprehensive longitudinal analysis of lupus autoantibodies, IFNα, and IFNγ from serum samples of 55 patients before and after clinical onset of SLE, with matched controls was performed." (PMID 31354738, 2019). "In MRL.Faslpr mice, a complete deficiency in IL-10 was accompanied by an enhanced IFNγ production in both CD4+ and CD8+ T cells, and an elevated anti-dsDNA antibody production with more severe clinical diseases, suggesting a protective role of IL-10 in lupus development." (PMID 31546763, 2019). "B-cells are capable of responding to IFNγ through the IFNγ -R and this mechanism has been shown to be important in driving B-cells in systemic lupus erythematosus (SLE), another autoimmune condition." (PMID 29293620, 2018). "Further evidence for the harmful role of excess IFNγ production in promoting B cell abnormalities and lupus diseases comes from studies in which deletion of IFNγ receptor in B cells abrogates spontaneous germinal centre formation, class switching of autoantibodies and nephritis in lupus-prone mice." (PMID 28456914, 2017).
lupus (continued). "Thus, we suggest that IFNγ might induce the expression of T-bet in B cells leading to their differentiation into CD11c+ B cells in lupus-like cGVHD mice." (PMID 28982388, 2017). "Using an amyloid-induced lupus model, Cao and colleagues have recently uncovered important roles of natural killer cells and IFNγ in SLE pathogenesis downstream of type I interferon response." (PMID 26648937, 2015). "MiR-146a is upregulated in RA; it is downregulated in systemic lupus erythematosus (SLE) where it is a negative regulator of IFNγ pathway." (PMID 25177699, 2014). "Therefore, while clearly there exists an intrinsic deficit in receptor expression by lupus DCs, IFNγ may contribute to aberrant MR expression in the subset of patients with high serum levels." (PMID 18811944, 2008). "High values of IFNγ and IL10 in mouse sera are characteristic of the severe stage of the disease with unstable levels and fluctuations of these important for lupus cytokines." (PMID 40806179, 2025). "Several other studies also discussed the expression profile of IFNγ in SLE patients or lupus mice (unknown treatment), showing that serum, urine, and CSF levels of IFNγ and the percentage of IFNγ+γδ+ T cells in SLE patients were increased than in controls." (PMID 38164134, 2023). "In vitro, IFN-I were shown to prolong survival of CD4+ T cells, and in a non-lupus model, IFN-I enhanced the clonal expansion of antigen-specific CD4+ T cells by increasing survival signals and leading to increased numbers of IFNγ producing cells." (PMID 35055071, 2022). "In addition, we found greater expression of ISG15 in the SLE NETs vs controls (p < 0.05), colocalization with H2B (r = 0.81) only in SLE samples and increased production of IFNγ in PBMCs stimulated with lupus NETs compared to healthy controls NETs." (PMID 33176801, 2020). "By utilizing MRL-lpr lupus model, we therefore investigated the role of EGR2 in the regulation of Th1 differentiation and Th1 cytokine IFNγ in the context of lupus." (PMID 32646370, 2020). "NETs containing ISG15 from SLE patients induce IFNγ production from diverse cellular subsets: To address the functional impact of ISG15 on the NETs from lupus patients, the production of IFNγ in subsets of T lymphocytes (CD4+ and CD8+) and NK cells was evaluated by multiparametric flow cytometry." (PMID 33176801, 2020). "The type II IFN, IFNG, also induces an IGS through its distinct IFNG receptor and has been shown to be important for pathogenesis in lupus mouse models." (PMID 31044165, 2019). "In the mouse model of lupus induced by the administration of NPA-bearing liposomes, spleen and mesenteric lymph node γδ T cells produce IFNγ and IL-17 and may play a role in inducing the germinal centers that produce anti-NPA IgG antibodies." (PMID 40943602, 2025). "Third, basophil depletion dramatically dampened both constitutive and PMA-ionomycin-induced IL-21 and IL-4 productions by TFH cells only in the lupus-like context, without significantly influencing their IFNγ or IL-17A production abilities." (PMID 38649353, 2024). "FVB/Fas−/− lupus-like mice had lymphadenopathy, splenomegaly, high proportion of CD4−CD8− T cells, IFNγ-producing T cells, and low proportion of Treg cells, and addition of IL-2 (25 ng/g bodyweight every 5 days, five times) restored the number of Treg cells and upregulated IFNγ expression." (PMID 38164134, 2023). "To functionally test this, we blocked IFNγ production using IL-18BP and type I IFN signaling using the anti-IFN α receptor 1 (IFNAR1) antibody anifrolumab, which is in clinical trials to treat systemic lupus erythematosus." (PMID 35930640, 2022). "Deletion of either miR-183C or miR-182 alone had no changes on the serum levels of IFNγ, IL-6, or other selected lupus-related cytokines, such as TNFα, IL-10, and IL-17." (PMID 35873462, 2022).